SHOX2 (SHOX homeobox 2)
Diseases named in the same sentence as SHOX2 in open-access papers (continued):
Sharing a sentence is not in itself a finding about the gene and the disease.
tumor (50 papers, 2010 to 2026). "The MTPC panel integrated four diagnostic modalities: methylation biomarkers (PTGER4 and SHOX2), tumor markers (CEA and CYFRA21-1), DNA ploidy analysis, and cytological examination." (PMID 41626161, 2026). "Quantitative DNA methylation levels for septin 9 (SEPT9) and short-stature homeobox 2 (SHOX2) in the ctDNA proved to be powerful prognostic and molecular staging biomarkers for identifying patients at a higher risk of tumour recurrence." (PMID 32415241, 2020). "TNM staging is inextricably linked to tumour formation, progression and regression, with stage IV patients having the most advanced disease, resulting in hypermethylation of the promoter regions of oncogenes such as SHOX2 and RASSF1A and hypomethylation of the proto-oncogene PTGER4 gene." (PMID 40386526, 2025). "Immune analysis showed that SHOX2 was closely correlated with the tumor mutation burden (TMB), microsatellite instability (MSI), neoantigen and neoantigens and immune checkpoint (ICP) in a variety of tumors and could influence the immunotherapy sensitivity of cancers." (PMID 37170390, 2023). "One of the genes that has been shown to be modulated by S. platensis is SHOX2, which is a tumor suppressor gene that inhibits cell proliferation and induces apoptosis." (PMID 41203700, 2025). "The methylation of genes such as RUNX3, GSTP1, SHOX2, DKK3, and MLH1 is associated with tumor progression and malignancy, with RUNX3 showing high promoter methylation in NSCLC tissues." (PMID 40136480, 2025). "Short stature homeobox 2 (SHOX2), an oncogene, has been demonstrated to be closely related to tumor metastasis." (PMID 39289763, 2024). "We next compared the diagnostic efficacy of the combined SHOX2 and RASSF1A methylation panels with that of multiple traditional serum tumor markers." (PMID 36691467, 2023). "Compared with normal samples, the SHOX2 expression showed a slight increase in tumor samples at Stage I (Wilcoxon test, P > 0.05) and a slight positive correction with the CT values (Spearman correlation, P > 0.05)." (PMID 35837113, 2022). "The promoter methylation levels of SHOX2 and RASSF1A were associated with their abnormal mRNA expression, and affected DNA instability, cell proliferation, apoptosis and tumor microenvironment in patients with LUAD." (PMID 35837113, 2022). "SHOX2 methylation and mRNA levels were significantly higher in PCa tissue and increased with tumor stage and grade, as well as in patients suffering from biochemical recurrence following radical prostatectomy." (PMID 36139516, 2022). "SEPT9 and SHOX2 were hypermethylated in PCa tissue and allowed discrimination of disease status, tumor stage and grade." (PMID 36139516, 2022). "To determine the expression level of SHOX2 in various types of tumors, we examined the differential expression of SHOX2 between tumor tissue and paired normal tissue using Oncomine and GEPIA online analysis tools." (PMID 34262939, 2021). "In mice implanted with SHOX2 knockdown cells, tumors were significantly smaller, as measured by tumor weight and volume, compared with mice that were implanted with knockdown control cells." (PMID 34465361, 2021). "Ten out of 11 tumor tissues showed higher methylation of the SHOX2 gene as compared to the normal lung tissues indicated by lower CT values (t-test p-value < 0.0001, Wilcoxon Rank-Sum test p-value = 0.0044)." (PMID 21047392, 2010). "SHOX2 can also directly activate the tumor metastasis-related gene WASF3, recruit the signal transduction-related factor STAT3 at its promoter site, and form a molecular complex with STAT3, which collectively enhances the activity of WASF3, promoting tumor metastasis." (PMID 39289763, 2024). "In the tumor tissues analyzed (n = 36), the occurrence of SHOX2 and RASSF1A methylation is 66.7%." (PMID 38996143, 2024). "TMB, MSI, neoantigen and ICP analyses showed that SHOX2 might be a promising target for the treatment of some tumor patients, especially in immunotherapy." (PMID 37170390, 2023).
tumor (continued). "However, SDC2 expression was significantly higher in normal tissues (P < 0.05), and SHOX2 expression was significantly higher in tumor tissues (P < 0.01)." (PMID 36803423, 2023). "Methylated SHOX2 in circulating cell-free DNA correlates with the tumor stage and prognosis." (PMID 36092911, 2022). "Interestingly, SHOX2 expression increased with tumor burden (p < 0.001 for both nodal metastasis and locally advanced disease) and grade (ISUP grading group p < 0.001)." (PMID 36139516, 2022). "Additionally, plasma SHOX2 and SEPT9 methylation levels were significantly associated with tumor and lymph nodes categories and histological grade, being SEPT9 methylation an independent prognostic factor for OS, risk of recurrence, and distant metastases." (PMID 36071985, 2022). "This may indicate that promoter hypermethylation of SHOX2 regulates its expression to a certain extent, but it is not the only regulatory mode, and there may be other ways leading to the upregulation of SHOX2 in tumor samples." (PMID 35837113, 2022). "When SCC was compared to AC, our results showed that a significant correlation was observed between the methylation of the SHOX2 gene and tumor histology, and its methylation frequency was significantly higher in SCC than in AC (OR = 4.32, 95% CI = 2.50 - 7.46, P < 0.001)." (PMID 28977861, 2017). "In cancer research, the development of laser microdissection (LMD) systems has addressed this dilemma and could be implemented in the future to study SHOX2 expression in distinct tumor cell types." (PMID 21426551, 2011). "An amplification of the SHOX2 gene locus together with the observed tumor-specific hypermethylation might explain the good performance of this marker in bronchial lavage samples." (PMID 21426551, 2011). "However, it has to be considered that SHOX2 mRNA levels were measured in homogenized (lysed) tumor tissues." (PMID 21426551, 2011). "SHOX2 and RASSF1A promoter methylation was associated with abnormal folic acid metabolism and DNA instability, which may affect DNA replication and repair, apoptosis and tumor immunity." (PMID 35837113, 2022). "Interestingly, restoration of WASF3 expression in MDA-MB-231 cells did not alleviate the suppressive effect of SHOX2 loss on tumor outgrowth, as evidenced by similar primary tumor sizes and Ki67-positive cancer cell numbers." (PMID 34465361, 2021). "SHOX2 and RASSF1A combined (LungMe®) methylation is significantly correlated to age, gender, tumor size, TNM stage, pathological type, pleural invasion and STAS." (PMID 38840077, 2024). "As a result, hypermethylated SHOX2 (mSHOX2) and SEPT9 (mSEPT9) genes within ccfDNA have been identified as potent pan-cancer biomarkers and proxies for circulating tumor DNA (ctDNA)." (PMID 38339235, 2024). "A variety of tumor datasets and online analytical tools, including SangerBox, TIMER2, LinkedOmic, GEPIA2 and cBioPortal, were applied to explore SHOX2 expression in various tumors." (PMID 37170390, 2023). "This indicated that high expression level of SHOX2 was related to decreased infiltration of stromal and immune cells in GBM, thereby resulting in high tumor purity." (PMID 37170390, 2023). "The methylation of HOXA1, IGFBP2, PTX3, TIMP1, SHOX2, and SH2D4A decreases with increasing tumor grade." (PMID 37091145, 2023). "In the NJDT cohort, methylation-positive patients of both individual SHOX2 and RASSF1A assays exhibited upregulation of folate acid metabolism and nucleotide metabolism in tumor samples." (PMID 35837113, 2022). "The combined assay had higher sensitivity on T&P samples than on tumor samples from LUAD patients, and its AUC was significantly higher than those of individual SHOX2 and RASSF1A assays, respectively (DeLong test, P < 0.05)." (PMID 35837113, 2022). "Then we explored the promoter methylation levels of SHOX2 and RASSF1A and their gene expression between normal and tumor samples at different stages in both cohorts." (PMID 35837113, 2022).
tumor (continued). "The promoter methylation level of SHOX2 and RASSF1A was significantly higher in tumor samples at stage I-II than that in normal samples." (PMID 35837113, 2022). "In the NJDT cohort, the promoter methylation CT values of both SHOX2 and RASSF1A in tumor samples at Stage I and II were significantly lower than those in normal samples (Wilcoxon test, P < 0.05)." (PMID 35837113, 2022). "We further evaluated the sensitivity of the SHOX2, RASSF1A, and PTGER4 methylation panel in plasma in different tumor stages." (PMID 34408226, 2021). "Detection sensitivity of SHOX2 and RASSF1A methylation in different histological subtype groups and tumor stage groups." (PMID 33425721, 2020). "We next used plasma from 89 patients with NSCLC and 25 tumor-free individuals (controls) for the study of both TMPRSS4 and SHOX2 methylation by ddPCR (1 mL for each gene)." (PMID 31817025, 2019). "In the present study, a similar approach was followed by selecting two candidate genes for methylation analysis in BTC, namely SHOX2 and SEPT9, which have been reported to be aberrantly methylated in other tumor entities." (PMID 27999621, 2016). "In our study, we demonstrated that the DNA methylation of SHOX2 and SEPT9 can accurately differentiate between tumor tissue from BTC patients and normal adjacent tissue with high specificity." (PMID 27999621, 2016). "miR-375 functions via targeting multiple genes involved in tumor development, including Yap, PDK1, 14–3-3-ζ and SHOX2." (PMID 25762642, 2015). "Since SHOX2 and SEPT9 seem to be suitable biomarkers in different tumor entities a benefit regarding the overall sensitivity is possible." (PMID 24386354, 2013). "Tumor tissue derived from patient #1 showed a very high methylation rate of 291% (referred to ACTB) and 46% (referred to total SHOX2 copies), respectively, as well as a strong copy number amplification of the SHOX2 gene (4.9 fold)." (PMID 21426551, 2011). "Notably, several homeodomain transcription factors were overexpressed in SFTs (ALX4, SHOX2, SIX1) and entire HOX clusters (HOXA, HOXC) were upregulated, as further confirmed by RNAPII profiling of a primary tumor tissue." (PMID 40875449, 2025). "The SHOX2 and RASSF1A methylation levels, tumor size and CTR values could predict the invasiveness of the tumor prior to surgery, thereby providing guidance for the surgical procedure." (PMID 38840077, 2024). "Similarly, SEPTIN9 participates in cytokinesis during the cell cycle, while SHOX2 is a transcription factor involved in proliferation, migration and colony formation and MGMT inhibits tumour formation." (PMID 38903861, 2024). "We focused on two methylation markers, SHOX2 and SEPT9, as proxies of circulating tumor DNA." (PMID 38339235, 2024). "Additionally, the methylation level of SHOX2, RASSF1A and LungMe® correlated with the high invasiveness of clinicopathological features, such as age, gender, tumor size, TNM stage, pathological type, pleural invasion and STAS." (PMID 38840077, 2024). "In both cohorts, SHOX2 expression increased and RASSF1A expression decreased in tumor samples." (PMID 35837113, 2022). "In summary, SHOX2 regulates the proliferation, apoptosis and metastasis of LUAD cells, and may facilitate pro-tumor biological processes." (PMID 35837113, 2022). "This indicated that the hypermethylation of SHOX2 and RASSF1A was highly tumor-specific." (PMID 33425721, 2020). "In addition, we developed a robust ddPCR method to quantify CpG methylation levels within the TMPRSS4 and SHOX2 promoters in blood and BAL that can differentiate between NSCLC patients and tumor-free individuals." (PMID 31817025, 2019). "SHOX2 methylation was significantly higher in tumor tissue than in NAT irrespective of tumor localization (p < 0.001) and correctly identified 71% of BTC specimens with 100% specificity (AUC = 0.918; 95% CI 0.865–0.971)." (PMID 27999621, 2016).
tumor (continued). "As a result, an increase of SHOX2 DNA copies in tumor cells compared to normal cells also increases the SHOX2 DNA methylation level in a mixed sample of tumor and normal cells as compared to the methylation level of normal cells alone." (PMID 21426551, 2011). "Contrarily, the SHOX2 expression seemed slightly elevated in tumor tissues, however, this was not statistically significant." (PMID 21426551, 2011). "Furthermore, no positive results for SHOX2 or RASSF1A methylation were detected in plasma samples from 19 non-tumor patients." (PMID 38996143, 2024). "The expression of SHOX2 was significantly higher in tumor samples at Stage I-II than that in normal samples, but there was a negative correlation between SHOX2 expression and its promoter methylation level in tumor samples at Stage I (Spearman correlation, P < 0.05)." (PMID 35837113, 2022). "Therefore, the promoter methylation of both SHOX2 and RASSF1A in early tumor samples were negative associated with their expression, respectively." (PMID 35837113, 2022). "An amplification of the SHOX2 or SEPT9 locus increases sensitivity compared to cell-based methods, i.e., cytology as four or more methylated copies of the SHOX2 or SEPT9 locus per tumor cell could exist." (PMID 26937257, 2016). "A downregulation of SHOX2 expression due to a hypermethylation of the SHOX2 region in tumor tissues could not be observed." (PMID 21426551, 2011). "In addition, increased levels of E-cadherin were consistently seen in xenograft tumor tissues derived from SHOX2 knockdown cells compared with the knockdown control cells, which were dramatically suppressed in xenograft tumors when WASF3 expression levels were restored in SHOX2 knockdown cells." (PMID 34465361, 2021). "The positive performance of SHOX2 DNA methylation as a biomarker in cytologically negative bronchial lavage samples might be due to the concerted effects of locus amplification and DNA methylation of SHOX2 in tumor cells." (PMID 21426551, 2011). "Interestingly, samples that were classified as 'cytologically negative' or 'inconclusive' due to no (or too few) visible tumor cell content could be identified as cancer-positive, based on their SHOX2 DNA methylation level." (PMID 21426551, 2011). "Hence, the positive performance of the SHOX2 DNA methylation as a biomarker in cytologically negative bronchial lavage samples might be due to a correlation of locus amplification and DNA methylation in tumor cells." (PMID 21426551, 2011).
cancer (49 papers, 2011 to 2025). A tumor composed of atypical neoplastic, often pleomorphic cells that invade other tissues. "Adenocarcinomas are rich in blood vessels, which usually show local infiltration and haematogenous metastasis earlier, accelerating cancer progression and causing hypermethylation of SHOX2 and RASSF1A, which inhibit cancer cell growth." (PMID 40386526, 2025). "The association of cancer diagnosis with the abnormal methylation status of the SHOX2 and RASSF1A genes has been studied in multiple sample types, including bronchoalveolar lavage fluid and formalin-fixed paraffin-embedded (FFPE) tissues." (PMID 36691467, 2023). "Genetic alterations of SHOX2 were identified in multiple types of cancers, including duplications and deep mutations." (PMID 37170390, 2023). "Several present researches reported that SHOX2 is associated with the tumorigenesis and progression of a variety of cancers." (PMID 37170390, 2023). "Previously, we probed the function of SHOX2 in cancer metastasis in zebrafish and found that loss of SHOX2 expression can inhibit the dissemination of MDA-MB-231 cells throughout the fish body." (PMID 34465361, 2021). "DNA methylation of SHOX2 not only provides diagnostic but also provides prognostic information for cancer patients." (PMID 25229548, 2014). "In pan-cancer analysis, SHOX2 expression positive correlated with CDKN2C (R = 0.41), COL6A1 (R = 0.35), COL6A2 (R = 0.37), DCHS1 (R = 0.37), MAPK7 (R = 0.34), PRRX1 (R = 0.37), RAB23 (R = 0.36) and RSRC1 (R = 0.36) via GEPIA2." (PMID 37170390, 2023). "As one of the most promising new biomarkers in the diagnosis of cancer, aberrant methylation of a set of genes, including SHOX2, RASSF1A, and SEPT9, has been transferred into clinical application." (PMID 36691467, 2023). "In order to investigate the correlation between SHOX2 mRNA expression and prognosis in a variety of cancers, GEPIA2 and Sangerbox portals were used." (PMID 37170390, 2023). "In this research, systematic bioinformatics analyses were performed to verify the prognostic significance and biological functions of SHOX2 in pan-cancers via a variety of datasets." (PMID 37170390, 2023). "The SHOX2 mRNA levels were significantly related to multiple TIICs in pan-cancers, including LGG and GBM." (PMID 37170390, 2023). "Secondly, we explored the correlation between SHOX2 expression levels and MSI, TMB or neoantigens to verify if SHOX2 was a predictor of immunotherapeutic responses in pan-cancers." (PMID 37170390, 2023). "Previous studies have revealed a relationship between cancer diagnosis and the detection of aberrant methylation changes in the SHOX2 and RASSF1A genes." (PMID 37182143, 2023). "Despite this, we believe that our study provided clinically relevant findings concerning the utility of methylation analysis of the promising pan-cancer biomarkers SEPT9 and SHOX2 in the diagnostic setup of PCa." (PMID 36139516, 2022). "This is critical for understanding how SHOX2 expression alter and how SHOX2 lead to cancers such as LUAD." (PMID 34262939, 2021). "In group 2, the significant reduction in SHOX2 methylation between cancer and cancer-adjacent specimen was observed in 16 cases." (PMID 33425721, 2020). "Our data showed that 23 of cancer tissues and 13 of cancer-adjacent specimens were classified as SHOX2 methylation positive, whereas 19 of cancer tissues and seven of cancer-adjacent specimens were classified as RASSF1A methylation positive." (PMID 33425721, 2020). "Twenty-three cancer tissues and 13 of cancer-adjacent specimens were classified as SHOX2 methylation positive with ΔCtSHOX2 ≤7.5." (PMID 33425721, 2020). "In group 1, high levels of SHOX2 methylation were observed in both cancer and cancer-adjacent specimens; besides, what were really noticeable were all seven cases in this group with at least one lymph node metastasis." (PMID 33425721, 2020).